LGALS3 (galectin 3)
Diseases named in the same sentence as LGALS3 in open-access papers (continued):
Sharing a sentence is not in itself a finding about the gene and the disease.
cancer (continued). "In this regard, the high affinity interaction between Galectin-3 (Gal-3), a member of β-galactoside binding protein family, and T antigen, located on the MUC1, is fundamental for TME regulation and cancer." (PMID 40001578, 2025). "In our study, we found that USP15 can interact with LGALS3 and activate the AKT/mTOR pathway by phosphorylating the AKT and mTOR proteins to exert cancer-promoting functions." (PMID 39794359, 2025). "USP15 stabilizes Lectin Galactoside-Binding Soluble 3 (LGALS3) by blocking its ubiquitin-proteasome system-mediated degradation, thereby activating the AKT/mTOR axis to promote cancer stemness, proliferation, and lenvatinib resistance." (PMID 41298358, 2025). "With regard to proteins released after sonication, several molecules were identified as candidate biomarkers in cancer US supernatants (Beta-2 microglobulin, CA125, CA19-9, CEA, CRP, Galectin-3, TIMP-1, uPA, and VEGF-A)." (PMID 40563629, 2025). "LGALS3 also plays a key role in TME immunosuppression and modulates a diverse range of cellular functions, involving cancer biology and cellular homeostasis." (PMID 38643145, 2024). "Furthermore, inhibition of C1GALT1 caused a significant reduction of galectin-3-mediated cell–cell aggregation and cell adhesion to basement proteins, while resulting in an increase of galactose-type lectin (MGL)-mediated heterotypic aggregates formed by macrophages with cancer cells." (PMID 38662050, 2024). "The interaction of LAG-3 with its ligands, such as MHC-II, Galectin-3, LSECtin, and FGL-1, highlights its potential as a therapeutic target and prognostic biomarker for cancer." (PMID 39660130, 2024). "First, we conducted pan-cancer analysis for LGALS3 expression level through an in-depth analysis of public databases and found that HCC has a high LGALS3 gene and protein expression level, which were then verified in clinical HCC specimens." (PMID 38643145, 2024). "For instance, Lgals3/galectin-3 promotes EMT in a carbohydrate-dependent manner and enhances the metastatic potential of cancer cells." (PMID 39595213, 2024). "In addition, galectin-3 levels in urine and stool may emerge as a biomarker for several cancers." (PMID 37189804, 2023). "In contrast, overexpression of β3 in the null cell line H727 promoted the growth of cancer cells, which were perturbed by shRNA KRAS or galectin-3 knockdown." (PMID 37371482, 2023). "Other immune checkpoint ligands, such as NECTIN2, LGALS3, LGALS9, and SELPLG, were highly expressed in cancer cells or other infiltrating immune/stromal cells." (PMID 36529697, 2023). "Other immune checkpoint ligands, NECTIN2, LGALS3, and LGALS9 were highly expressed in cancer cells or other infiltrating cells." (PMID 36529697, 2023). "In both paired and unpaired samples of HCC patients, EZH2, G6PD, LGALS3 and PSMD14 were highly expressed in the cancer and lowly expressed in the paracancer, with statistically significant differences." (PMID 37853322, 2023). "Other immune checkpoint ligands or receptors, SELPLG, HAVCR2, LGALS3, and LGALS9, were highly expressed in cancer cells or other infiltrating cells." (PMID 36529697, 2023). "The top five ligands targeting CD8+ T-cells by mesenchymal cancer cells from infiltrated tumors were HLA-C, HLA-A, CD59, LGALS3, and B2M." (PMID 38086828, 2023). "Western blotting was used to investigate the expression levels of galectin-3 and GSK3B proteins in the normal cell line, (SVGp12), and in cancer cell lines (GBM8401, GBM8901, U87-MG, and G5T)." (PMID 37185758, 2023). "Since literature evidence supports the important roles of CD44, BATF, LGALS3, and NFKBIZ in cancer, we decided to validate the expression of these genes with independent experimental methods." (PMID 36982699, 2023). "Taken together, our findings indicate that LGALS3 expression is correlated with the EMT of cancer cells in vivo and in vitro, and that EMT drives expression of LGALS3 in HGSOC cells." (PMID 38086828, 2023).
cancer (continued). "Of all the cancer cell lines used, GBM8401 and U87MG demonstrated the highest expression level of both galectin-3 and GSK3B." (PMID 37185758, 2023). "After the analysis of fold changes, upregulation in the mRNA level of LGALS1, LGALS3, LGALS4, LGALS8, and LGALS9 was detected in cancer patients compared to normal ovarian tissue." (PMID 36050693, 2022). "For example, binding of galectin-3 to the oncofetal galactose-β1,3N-acetyl-galactosamineα-Thr/Ser on the transmembrane mucin protein MUC1 in cancer cells induces MUC1 cell surface polarization." (PMID 36291660, 2022). "In this systematic review and meta-analysis, we assessed the value of galectin-3 and MPO in monitoring cardiotoxicity in cancer patients." (PMID 36551214, 2022). "The level of proteins involved in cancer metastasis, including EMT and galectin-3, were compared among CCA cells and 2D- and 3D-based culture systems." (PMID 36713574, 2022). "The absence of a difference in pre-treatment and post-treatment galectin-3 levels, and the weaker relationship between galectin-3 evaluations and the risk of cardiotoxicity, suggest that galectin-3 is likely not a useful biomarker of cancer-therapy-related cardiotoxicity." (PMID 36551214, 2022). "On the one hand, it is probable that the use of galectin-3 to diagnose cardiovascular illness in cancer survivors in clinical practice may be impacted by the overlap between the pathophysiology of cardiovascular disease and cancer, including inflammation and cell proliferation." (PMID 36551214, 2022). "In euglycaemia, all-cause mortality was increased by 17% after adjustment for age, sex, traditional CVRF, EF and log(E/E′ ratio) and by 20% per SD increase of galectin-3 after adjustment for age, sex, traditional CVRF, cancer and eGFR." (PMID 34561496, 2021). "LGALS3-expressing cells also possess higher ALDH1 activity, which often correlates with a dedifferentiated cancer stem cell phenotype, than do their LGALS3-negative counterparts." (PMID 34290978, 2021). "This down-regulation in the CxRx–OTME-Chip was close to the KO-g3 cancer cells available from KO–OTME-Chip, where the GPVI–galectin-3 interaction was disturbed via KO." (PMID 34290095, 2021). "The transcript levels of Galectin-3 (LGALS3) and Galectin-3 binding protein (LGALS3BP), important regulators of innate immune responses often found upregulated in various cancer types 56, were significantly decreased in MLL-r cells." (PMID 34646384, 2021). "Revacept significantly reduced ECM invasion and proliferation rate of the cancer cells, suggesting that GPVI inhibition was also preventing the consequence of GPVI–galectin-3 interaction." (PMID 34290095, 2021). "We reviewed data on the relationship between PD-L1, B7-H3, B7-H4, IDO1, Galectin-3 and -9, CEACAM1, CD155, Siglec-15 and ADAM17 expression with cancer development in complex with the results of clinical trials on their inhibition." (PMID 34943606, 2021). "Immunohistochemical analysis, incorporating 83 cases of histologically confirmed FPTLs out of which 20 carcinomas, 51 benign FPTLs (38 HN and 13 FA), and 12NIFTP were separated from each others using four immunostains (HBME-1, CK19, Galectin-3, and CD56)." (PMID 34711014, 2021). "These cells interact with some secreted proteins like galectin-3, matrix metalloproteinases (MMP), osteopontin and, TGF-β responsible for cancer development and produce an extracellular matrix (ECM) that creates an environment to spread cancer." (PMID 33409265, 2020). "For dysregulated KRAS-RalB-NF-κB signaling in FGβ3 cells, galectin-3 plays a critical role in clustering integrin αvβ3 to induce KRAS and enable multiple processes in cancer cells." (PMID 32514015, 2020). "Given the overexpression of Galectin-3 in CRC, it is necessary to elucidate the biological role in cancer cells." (PMID 28146425, 2017). "Thus, anti-Galectin-3 therapy may be an effective method for cancer treatment." (PMID 28701735, 2017).
cancer (continued). "Many studies have reported that the binding of galectin-3 with MUC1 triggers MUC1-dependent intracellular signaling in cancer cells and facilitates adhesion of cancer cells to each other and to endothelial cells." (PMID 27754373, 2016). "Recently, another study demonstrated that galectin-3 knockdown potentiates the response to gefitinib (EGFR-tyrosine kinase inhibitor) treatment in esophageal squamous cancer cells, a type of cancer that overexpresses EGFR." (PMID 27242966, 2016). "Tyrosine phosphorylated Cav1 (pCav1) functions in concert with Galectin-3 (Gal3) and the galectin lattice to stabilize focal adhesion kinase (FAK) within focal adhesions (FAs) and promote cancer cell motility." (PMID 25942420, 2015). "These synthetic peptides, although not modified with any galactose residues, were reported to bind to the galectin-3 CRD and inhibit galectin-3-TF interaction, and prevent galectin-3-mediated cancer cell adhesion, aggregation in vitro and metastasis in vivo." (PMID 26160844, 2015). "Galectin-3 showed high expression at the mRNA and protein levels in HCC cancer tissues and cell lines." (PMID 25260879, 2014). "Further study will be critical in determining the role and regulation of neogenin-1 in various cancer types, as well as the roles of neogenin-1, galectin-3 and HSF-1 regulation in cancer metastasis." (PMID 24930499, 2014). "Since MCP has been shown to target galectin-3, several works were dedicated to delineate MCP-induced possible re-sensitization of cancer cells to different cytotoxic molecules." (PMID 24115933, 2013). "Nevertheless, the intensive galectin-3 labeling in the majority of samples and the strong expression in RCC-FG1 cells suggests that this lectin is involved in cancer progression and cellular differentiation." (PMID 21958686, 2011). "Taken all together, these results suggested that galectin-3 increased the expression of both PAR-1 and MMP-1, and that the increased MMP-1 expression activated PAR-1 signaling, which in turn, facilitated cancer cell invasion." (PMID 21966428, 2011). "We postulate that this effect on proliferation was due to inhibition of galectin-3 which contains the NWGR domain characteristic of the Bcl-2 family and has been shown to inhibit apoptosis and increase chemoresistance in cancer." (PMID 21765917, 2011). "Moreover galectin-3 expression could play different roles in different carcinomas types." (PMID 22024187, 2011). "On the other hand, Galectin 3, a cell adhesion molecule, was detected to down-regulated in AT1K pre-neoplastic, CA1h low- and CA1a high-grade cancer cell lines compared to normal cells." (PMID 20543960, 2010). "On the other hand, when these markers were combined (e.g., galectin-3 + HBME-1; HBME-1 + CK-19; galectin-3 + HBME-1 + CK-19), several investigators reported improved sensitivity and specificity for the detection of cancer seen on tissue or FNA samples." (PMID 24281099, 2010). "EP300, ISGF3G, STAT1, and STAT3 are up regulated in 8/13 of cancer models, while ATM, BAX, BCL2L11, HTATIP2, LGALS3, MAPK1, and TP73L are down regulated in half of cancer models." (PMID 19402918, 2009). "The results show that the panel of galectin-3 + HBME-1 has the highest sensitivity and specificity of immunoexpression in all benign lesions versus malignant tumors, 90.7% and 75%, respectively." (PMID 19826479, 2009). "Our analysis showed that AATF, LGALS3, and SRC are up regulated in 8/13 of cancer models, and CDC2L2, E2F6, LGALS9, PDCD8, RELB, TRADD, and TRAF2 in 7/13." (PMID 19402918, 2009). "Our results demonstrate that LSPs induce widespread LMP, which subsequently activates the Galectin‐3 (Gal3)‐Trim16 signaling axis to trigger autophagic cell death in cancer cells—independent of classical apoptotic pathways." (PMID 41082270, 2026). "All cancer-type APTs had positive staining for PGP 9.5 and galectin-3; however, these markers were not specific to cancer-type tumors." (PMID 40434298, 2025).
cancer (continued). "Ongoing investigations are exploring how MGAT5 and galectin-3 modulate other key receptors, including VEGFR and integrins, in cancer models, which could provide additional therapeutic strategies." (PMID 41408046, 2025). "Among the 15 members of the lectin family, Galactin-1 and Galectin-3 appear to be the most important factors in cancer biology but were not validated in NETs." (PMID 40507492, 2025). "In our cohort, infection- and malignancy-related deaths accounted for the majority of non-CV deaths, and median galectin-3 levels in these patients were comparable to those who died from CV causes." (PMID 41158187, 2025). "In cancer contexts where TGF-β1 plays a major role in initiation and maintenance of EMT, patients may also benefit from LGALS3 inhibitors." (PMID 38086828, 2023). "Galectin-3 and MGL are both known active regulators in cancer progression." (PMID 37612278, 2023). "Galectin-3 specifically is an attractive target for cancer research because it is not expressed in high amounts in the body beyond early development." (PMID 37445799, 2023). "However, as novel biomarkers, the roles of galectin-3 and MPO in the monitoring of cancer-therapy-related cardiotoxicity remain controversial." (PMID 36551214, 2022). "The present meta-analysis reveals that MPO is a useful biomarker for the early detection of cancer-therapy-related cardiotoxicity, whereas galectin-3 is not." (PMID 36551214, 2022). "Hence, a meta-analysis was performed to assess the monitoring value of galectin-3 and MPO in cancer-therapy-related cardiotoxicity." (PMID 36551214, 2022). "The present meta-analysis highlights MPO as a promising biomarker of cancer-therapy-related cardiotoxicity, whereas the available evidence does not yet consistently support a beneficial role for galectin-3, potentially due to significant heterogeneity." (PMID 36551214, 2022). "We first examined the expression and activity of galectin-3 over the course of our 72-hour timeline of exposure of cancer cells to extravasated platelets and found that galectin-3 expression was conserved and did not change over time." (PMID 34290095, 2021). "Although focal galectin-3, HBME-1, and cytokeratin-19 expression were encountered in benign FPTLs, diffuse positive reactions for these three markers were more characteristic of carcinomas." (PMID 34711014, 2021). "In the tumor microenvironment, extracellular galectin-3 interacts with distinct ECM molecules and surface glycoproteins, such as growth factor receptors, integrins, cadherins, and members of Notch family, probably favoring the biology of cancer cells." (PMID 32079295, 2020). "Five additional proteins were studied: carcinoma stem cell markers: TRA-1-60, CD326 (epithelial cell adhesion molecule, EpCAM), galectin-3 (GAL-3), the immune checkpoint inhibitor CD274 (programmed cell death ligand-1, PD-L1) and carcinoma marker pan-keratin (cytokeratins)." (PMID 31527554, 2019). "Fourthly, some essays studied galectin-3 combined with another biomarker in prognostic outcome analyses, showing galectin-3 was not an independent factor affecting the prognosis of cancer patients." (PMID 30410421, 2018). "Overall, a negative spatial relationship between galectin-3 expression on cancer cells and CD3 + cells was identified (mean Spearman’s rho = −0.40)." (PMID 30254278, 2018). "The negativity does not mean that the cytopathology report should be considered 100% benign because some of the malignant neoplasms were missed by Galectin-3 test and showed a false negative reactivity." (PMID 28811803, 2017). "The positive rate of Vimentin, VE-cadherin, and Galectin-3 expression in the presence of Runx2 was higher than in cancer cells that did not express Runx2, while the positive rate of E-cadherin in Runx2-positive cells was lower than in the Runx2-negative group." (PMID 28264434, 2017).
cancer (continued). "These chemically-modified heparin derivatives, which show no detectable anti-coagulant activity and cytotoxicity, bind to galectin-3 carbohydrate recognition domain (CRD) and inhibit galectin-3-mediated cancer cell adhesion and angiogenesis in vitro and metastasis in vivo in a mouse model." (PMID 26160844, 2015). "Galectin-3-mediated MUC1-C–EGFR binding might elicit EGFR-mediated downstream signaling pathways that are involved in tumorigenesis and cancer cell growth." (PMID 24639126, 2014). "Galectin-3 interacts with MUC1 and regulates MUC1 expression and function in cancer cells." (PMID 25499743, 2014). "It is possible that galectin-3 does not discriminate between non-cancer controls and other categories of PCa." (PMID 23625538, 2013). "Because the polyclonal antibody (but not the monoclonal antibody) recognizes cleaved galectin-3, we demonstrated that using a single antibody is not enough to provide the complete picture of the significance of this protein in cancer progression." (PMID 23625538, 2013). "Many of them, if not all, are due to its binding to the pleiotropic galectin-3 protein which is overexpressed in cancer." (PMID 24115933, 2013). "An increasing number of publications are suggesting that galectin-3 (Gal-3) and soluble cadherin fragments, such as E-cadherin (sE-CAD) and N-cadherin (sN-CAD), may be considered as cancer markers." (PMID 22340429, 2012). "Besides the therapeutic roles against cancer, MCP has been shown to remove toxic metals from the body, and reduce experimentally induced kidney injury and fibrosis in vivo by reducing galectin-3 levels." (PMID 21816083, 2011). "The distribution of galectin-3 mRNA levels in normal and cancer tissues are higher than for Beclin1; there is no indication that this implies that galectin-3's function in apoptosis interferes with Beclin1's autophagy functions." (PMID 22039439, 2011). "We also found that combination panels of 2 or 3 of these markers (galectin-3+ HBME-1; galectin-3+ CK19; HBME-1+ CK19 or galectin-3+ HBME-1+ CK19) do not significantly improves the sensitivity or specificity of immunoexpression in malignant tumors." (PMID 20181018, 2010). "In addition, we found that galectin-3 was somewhat more strongly and diffusely positive in PTC than in FC and FVPC, and expression in FA/HA was more focal and less intense than in malignant tumors." (PMID 20181018, 2010). "In fact, some of the glycosylated forms of hC4.4A as expressed on cancer cells did not bind galectin-3." (PMID 17912244, 2007). "The discovery of a novel class of non-carbohydrate galectin-3 inhibitors without cytotoxicity shown in this study therefore not only offers great opportunities for therapeutic treatment of cancer but also of those diseases that are also in high unmet clinical needs." (PMID 41023585, 2025). "However, a systematic, pan-cancer analysis of the molecular and clinical consequences of LGALS3 dysregulation is lacking." (PMID 41153387, 2025). "LGALS3 was not statistically significant for OS of 22 other cancer types patients." (PMID 38643145, 2024). "In-depth analysis of cell communication networks of cancer cells signaling to the CD8+ T cell population revealed that a large portion of the communication is facilitated by the mesenchymal cells and is mediated by HLA II molecules and LGALS3 communicating with the LAG3 receptor complex." (PMID 38086828, 2023). "The binding of galectin-3 to β1,6GlcNAc-branched N-glycans on β4 integrin induces the formation of a supramolecular complex consisting of α6β4 integrin, EGFR, and laminin-332, which in turn promotes cancer cell adhesion and migration via the activation of PI3K and ERK signaling pathways." (PMID 38136623, 2023). "E-cadherin, B-catenin and galectin-3 may prove to be important biomarkers that have not yet been jointly evaluated in this type of cancer." (PMID 38144531, 2023).